IL10 (interleukin 10)
Diseases named in the same sentence as IL10 in open-access papers (continued):
Sharing a sentence is not in itself a finding about the gene and the disease.
Sepsis (continued). "Similarly, splenic DCs from septic mice are unable to secrete IL-12, but they can release a significant amount of IL-10 compared with DCs obtained from control mice, suggesting that sepsis can abrogate DCs inducing Th1 cell polymerization." (PMID 32197507, 2020). "Furthermore, the contents of TNF-α, IL-6, and IL-10 were detected in order to study the inflammation in mice with sepsis." (PMID 33376482, 2020). "Furthermore, it downregulated the transcriptions of proinflammatory cytokine IL-6, TNF-α, and Il-1β and upregulated IL-10 transcription in the liver of sepsis mice." (PMID 32457606, 2020). "Also, prior studies observed that serum IL‐6 and IL‐10 levels were remarkably up‐regulated in patients with sepsis." (PMID 32383354, 2020). "Moreover, miR-30a was demonstrated to suppress IL-10-induced cytokine release via regulating STAT1-MD-2 in monocytes of sepsis." (PMID 33817242, 2020). "We consider that the increase of IL-10 in the sepsis mouse was realized to protect the host from tissue damage during acute phases of immune responses, and SST could further enhance this protective progress." (PMID 33376482, 2020). "This may explain why blocking IL10 was so efficient in reducing the accumulation of MDSCs only in late sepsis." (PMID 32931721, 2020). "MAPK signaling is suppressed by blocking the phosphorylation of JNK and p38, which decreases the levels of the pro-inflammatory cytokines IL-6 and TNF-α and increases the level of the anti-inflammatory cytokine IL-10 to subsequently alleviate the inflammation in subjects with sepsis-induced ARDS." (PMID 32319516, 2020). "Moreover, CLP per se up‐regulated IL‐10 and TGF‐β1 levels in mice, while higher levels of TGF‐β1 and IL‐10 were observed after IL‐38 administration in the setting of sepsis." (PMID 31880383, 2020). "Identified molecular targets of miR‐193a‐5p included IL‐10, which is known to correlate with the CURB‐65 score and is associated with increased mortality in patients with CAP37 and mTOR, which has been shown to be down‐regulated in sepsis due to CAP." (PMID 32916773, 2020). "We found that activation of α7 nAChR on macrophages affects the expression of membrane proteins, such as HLA-DR, CD14, CD11b, and CD54, and also induces changes in the IL-10 production, all being involved in immunosuppression and hyperinflammation during sepsis." (PMID 32230846, 2020). "In our previous study, we also indicated that eight functional polymorphisms (IL1B-1470, IL1B-511, IL1B-31, IL4-589, IL6-572, IL8-251, IL10-819, and TNFA-308) could be combined together to predict the risk of sepsis and organ dysfunction after trauma." (PMID 33281864, 2020). "SST could relieve the injury, the decrease of SSTRs, and the increase of TNF-α and IL-6 induced by sepsis and also further enhanced the expression of IL-10." (PMID 33376482, 2020). "The paper entitled “Bone marrow stromal cells attenuate sepsis via prostaglandin E2-dependent reprogramming of host macrophages to increase their interleukin-10 production” had been cited for 1110 times since its publication, which was the most cited papers in related field." (PMID 31892843, 2020). "Furthermore, the remarkably increased contents of IL‐6 and IL‐10 were observed in the circDNMT3B‐si group, compared with the sepsis group." (PMID 32383354, 2020). "This speculation is based on previous studies, in which the plasma concentration of IL-10 was decreased by the administration of antimonoclonal TNF-α antibodies in chimpanzees with sepsis." (PMID 32766286, 2020). "IL-10 thus likely appears to play a major role in sepsis-induced immunosuppression." (PMID 33613540, 2020). "Neonates with sepsis, pneumonia and necrotising enterocolitis demonstrated high levels of Il-10." (PMID 32228505, 2020). "However, male KO mice had significantly higher levels of TNFα and IL-6 after sepsis when compared to male WT septic mice, while levels of IL-10 and KC were similar in both WT and KO male mice." (PMID 32117320, 2020).
Sepsis (continued). "As previously shown, blocking IL-10 could reverse sepsis-induced immunosuppression and improved survival in a clinically relevant animal model of sepsis." (PMID 32346013, 2020). "Together, these results call for further investigation of the theory defended by different groups suggesting that IL-10 plays a role in decreased MHC class II expression in sepsis either through intracellular sequestration of mHLA-DR or via inhibition of its transcription." (PMID 33613540, 2020). "Likewise, adjunctive PTX to GENT when administered simultaneous with sepsis initiation significantly decreased the TNF-to-IL-10 concentration ratio in the lung compared to saline controls." (PMID 33072121, 2020). "In this article, we will focus on the pathological role of MDSC expansion in chronic inflammatory conditions including cancer, sepsis/infection, autoimmunity, asthma and ageing, as well as some of the mechanisms by which MDSCs/IL-10 contribute to the disease progression in such conditions." (PMID 32931721, 2020). "However, elevated IL-10 levels can also increase the incidence of postoperative infection and sepsis." (PMID 33228727, 2020). "Elevated IL-10 levels have also been associated with impaired long-term functional performance following TKA as well as in patients with traumatic bone injuries, which was predictive of sepsis development." (PMID 32640676, 2020). "We tested whether increasing Hotairm1 levels in early sepsis Gr1+CD11b+ MDSCs could affect Arginase 1 and IL-10 expressions." (PMID 33335790, 2020). "In addition, the IL-10 UC-MSCs secreted substantially greater amounts of IL-10 in vitro than did naïve UC-MSCs, and this was further enhanced in the presence of macrophages from healthy volunteers and in patients with sepsis." (PMID 31200579, 2019). "In particular, IFN-γ as well as IL-10-activated CBMΦ completely fail to increase glycolysis and furthermore show reduced activation of the mTOR pathway, which is important for survival in sepsis." (PMID 30976008, 2019). "In sepsis, inflammatory stimuli also activate counter-inflammatory cytokines such as IL-10 that can downregulate the host inflammatory response, and may have a key role to play in controlling the pro-inflammatory cytokine response." (PMID 30820191, 2019). "This sepsis-induced immunosuppressive state may be further mediated by the release of anti-inflammatory cytokines (e.g., IL-4 and IL-10)." (PMID 30885252, 2019). "The in situ decrease (or lack of expression) in Th1 pro-inflammatory cytokines (IL-6, IFN-y, IL-1β, IL-2r, and IL-12) and the increase in IL-10 indicate that there is an inhibition of the innate and acquired immunity during the acute and severe phases of leptospirosis and sepsis." (PMID 31114579, 2019). "On the other hand, correlation analyses of the DNA methylation profiles in relation to IL-10 and IL-6 levels, which are increased in patients with sepsis, suggest a potential mechanism downstream to these cytokines participating in the defective generation of DNA methylation alterations." (PMID 31665078, 2019). "The increased IL-10 and IL-4 anti-inflammatory cytokines expression corroborates to other previous authors, these cytokines contributes to decreased mortality rate in endotoxemia or sepsis." (PMID 31191818, 2019). "Our data show an increase in NO and IL-10 levels during CMV reactivation in sepsis, corroborating with several studies pointing out that CMV infection is able to stimulate NO production in several cell types, but such mediator does not act as a microbicidal molecule on this virus." (PMID 31227794, 2019). "We identified significantly increased levels of IL-10 and IL-6 in patients with sepsis." (PMID 31665078, 2019). "Thirdly the sepsis-induced expansion of immunosuppressive cell populations such as regulatory T cells, IL-10 producing B-cells and myeloid derived suppressor cells (MDSC) could inhibit T cell effector functions." (PMID 30730978, 2019).
Sepsis (continued). "In canine studies modeling sepsis through injection of lipopolysaccharide (LPS), treated dogs had greater blood IL-6, IL-10, TNF-α, and KC-like concentrations up to 4-h post-injection and greater CCL2 up to 24-h post-injection, when compared to placebo-treated dogs." (PMID 31316998, 2019). "DNA methylation profiles correlate with IL-10 and IL-6 levels, significantly increased in monocytes in sepsis, as well as with the Sequential Organ Failure Assessment score; the observed changes associate with TFs and pathways downstream to toll-like receptors and inflammatory cytokines." (PMID 31665078, 2019). "In addition, MSCs also had beneficial effects by increasing IL-10 production from lung monocytes and macrophages in a sepsis mouse model." (PMID 31611920, 2019). "In addition, in the peritoneal fluid and serum of OMV-induced sepsis mice, NV treatment increased IL-10 secretion both locally and systemically." (PMID 31370884, 2019). "Also, administration of IL-10 after induction of sepsis was found to decrease lethality in mice through suppressing the elevation of systemic TNF-α." (PMID 31370884, 2019). "Taken together, these data indicate that MSC-derived NVs have beneficial effects in a mouse model of sepsis by upregulating the IL-10 production, suggesting that artificial NVs may be novel EV-mimetics clinically applicable to septic patients." (PMID 31370884, 2019). "A key role for the MSC-mediated, increased production of IL-10 has been demonstrated in a sepsis model in mice where IL-10 neutralization reversed the beneficial effect of bone marrow-derived MSCs on overall survival after induction of sepsis via cecal ligation and puncture (CLP)." (PMID 31214172, 2019). "We previously found that CD11b-activated Src signaling could inhibit inflammatory cytokine in sepsis and could promote anti-inflammatory cytokine IL-10 in mice model of colitis." (PMID 31781099, 2019). "In fact, several other studies showed that MRS could increase the IL-10 production in different diseases such as postoperative cognitive dysfunction, LPS-induced sepsis, carbon tetrachloride-induced liver injury, and chronic inflammatory pain." (PMID 31182999, 2019). "When they examined the blood of a small number of patients who had been diagnosed with sepsis 5–10 months prior, they found that sepsis survivors had significantly higher concentrations of both IL-10 and IL-33 and higher circulating Treg numbers compared to previously healthy patients." (PMID 31507598, 2019). "Interestingly, IL-10, an anti-inflammatory cytokine, was 2.5-fold higher in sepsis survivors compared to NSC (p=0.011)." (PMID 31793435, 2019). "IL-10 has been suggested as an important regulator in sepsis." (PMID 29868038, 2018). "Our data reveal that sepsis induces a long lasting increase in IL-10+ B cells and MDSCs." (PMID 29466409, 2018). "Importantly, the rise of serum IL-10 along with IL-6 and IL-8 is part of a combined proposed predictor score for fatal outcomes in human sepsis, and MEDI3902 administration in the present study resulted in downregulation of all three transcripts." (PMID 29483116, 2018). "Interestingly, the expanded IL-10+ B cell population remained for almost one month after sepsis induction and is, thus, likely to contribute to long-term post-sepsis immunosuppression." (PMID 29466409, 2018). "However, some therapeutic strategies to block aberrant cytokines have been demonstrated efficacy in experimental sepsis: blocking IL-10, an immuno-suppressive cytokine, improves survival during CLP63." (PMID 29410422, 2018). "In the LPS model of sepsis, there was markedly reduced survival in the Il10rb−/− mice, which is consistent with findings in IL10 deficient mice, but which has not been previously reported." (PMID 29907154, 2018). "Interestingly, although many sepsis patients displayed evidence of haemolysis, IL-10 (as a marker of regulation of inflammation) appeared to be the main driver of HO-1 induction." (PMID 30046137, 2018).
Sepsis (continued). "We recently demonstrated the beneficial role of IL-10 producing B-1a cells in sepsis by controlling the systemic levels of pro-inflammatory cytokines, chemokines and bacterial loads, while their role in ALI remained unknown." (PMID 30134811, 2018). "Interestingly, in a murine Cecal Ligation and Puncture (CLP)-induced sepsis model, the inhibition of IL-10 at the time of CLP worsened mortality rate whereas it increased survival when administered 12 h later." (PMID 29974037, 2018). "The levels of TNF-α, IL-6 and IL-10 were significantly higher in the miR-31 mimic group (all p < 0.05) while significantly lower levels were observed in the miR-31 inhibitor group when compared with the sepsis group (all p < 0.05)." (PMID 30340459, 2018). "We found that, in a previous study, exogenous Cit alleviated the release of proinflammatory cytokines (TNF-α, IL-1β, and IL-6) in early sepsis and increased the release of late-stage anti-inflammatory cytokines (IL-4 and IL-10) to alleviate the inflammatory response of septic rats." (PMID 30498752, 2018). "Sepsis induced an increase in IL-10+ B cells, which was enhanced and prolonged by IL-7 treatment." (PMID 29466409, 2018). "We hypothesised that Treg cells might produce large amounts of IL-10 following major surgery as these cells have previously been suggested to promote immune-dysfunction following both traumatic injury and sepsis." (PMID 30212506, 2018). "More studies are required in order to elucidate the role of IL-10 in sepsis affecting males since the increased levels of this cytokine are associated with a worse outcome by exerting suppression in the immune response, whereas its reduction leads to a non-controlled pro-inflammatory response." (PMID 29925409, 2018). "In the current study, we observed significant relationships between plasma levels of MCP-1, sCD14, HBP, and cortisol and the source of sepsis, whereas the well-established inflammatory cytokines (i.e., IL-6 and IL-10) demonstrated relatively low detectability in our cohort of septic patients." (PMID 29769838, 2018). "Interestingly, 1 month post-sepsis both the frequency and the numbers of IL-10+ B cells were higher in IL-7-treated septic mice than in sham mice and remained elevated even 3.5 months after sepsis induction." (PMID 29466409, 2018). "Our findings that Th1 and Th17 cells are profoundly suppressed by endotoxemia whereas IL-10 production by T-cells remains unaffected, may add to the understanding dysregulated immunity sepsis." (PMID 29868038, 2018). "Therefore, IL-10, one of the strongest anti-inflammatory cytokines, can be detected in the blood during the acute phase of sepsis." (PMID 29769838, 2018). "Moreover, sepsis-surviving patients have more Treg cells, IL-33 and IL-10 in their peripheral blood." (PMID 28374774, 2017). "IL10/TNF ratio increased progressively in patients with increasing sepsis severity and mortality." (PMID 31058274, 2017). "Furthermore, the group that received MSCs had a greater increase in IL-10 than the untreated sepsis group." (PMID 29273091, 2017). "However, IL-33-induced IL-10-secreting M2 macrophages increase the expansion of Treg cell population, thereby contributing to the development of long-term sepsis-induced immunosuppression." (PMID 28374774, 2017). "Interestingly, sepsis groups demonstrated a significant elevation in creatinine, IL-6 and IL-10 when compared to hour-adjusted control groups, thus indicating a possible dysfunction of more organs including the kidneys." (PMID 29136027, 2017). "Only IL-6, IL-8, IL-10, and procalcitonin were useful as discriminators of sepsis." (PMID 28769538, 2017). "PGE2 altered the activity of tissue-resident macrophages with a pro-inflammatory response and stimulated the secretion of an array of anti-inflammatory mediators such as IL-10 and IL-1 receptor antagonist, reducing the systemic effects of sepsis and thus improving survival." (PMID 29273091, 2017).
Sepsis (continued). "We then examined whether IL-10 participates in the pathogenesis of immune dysfunction in sepsis-surviving mice." (PMID 28374774, 2017). "Finally, sepsis-surviving Il10−/− mice show significantly lower bacterial burdens in the lungs and spleen and higher survival rate to challenge with L. pneumophila infection than the WT control mice." (PMID 28374774, 2017). "Therefore, we combined with IL-10 and lymphocyte to reflect the status of sepsis-induced immunosuppression." (PMID 28628675, 2017). "Previous studies in experimental model of sepsis demonstrated the ability of MSCs to reprogram macrophages from a pro-inflammatory state to an anti-inflammatory state through the release of PGE2, causing increased secretion of IL-10." (PMID 29273091, 2017). "Several studies demonstrate that the protective role of MSCs in sepsis may be attributed to the soluble paracrine factors released by these cells, such as interleukin (IL)-10, prostaglandin E2 (PGE2), tumor necrosis factor (TNF)-α and IL-6." (PMID 29273091, 2017). "Excessive secretion of IL-10 may contribute to immunosuppression typical for later stages of sepsis." (PMID 29312312, 2017). "IL-8, IL-6, IL-10, and procalcitonin are useful as early biomarkers of sepsis." (PMID 28769538, 2017). "Therefore, we cannot exclude the possibility that IL-33-induced MDSCs also participate in the production of IL-10 and expansion of Treg cells in sepsis survivors." (PMID 28374774, 2017). "Therefore, to better understanding the change of physiopathology in sepsis, it is good way to combining with IL-10 and lymphocyte." (PMID 28628675, 2017). "Importantly, patients who survive sepsis have more circulating Treg cells and higher concentrations of IL-33 and IL-10 in their serum compared to healthy non-sepsis individuals." (PMID 28374774, 2017). "Secretion of IL-10 in sepsis could limit and ultimately terminate inflammatory responses, which called as anti-inflammation cytokine." (PMID 28628675, 2017). "In our TLR4+896A/G variant allele carriers with severe sepsis, a negative correlation was noted between plasma IL-10 and LPS-stimulated CD16- (classical) monocyte HLA-DR expression." (PMID 27861595, 2016). "Elevated levels of IL-10 protein have been found in children after sepsis, trauma or major surgery." (PMID 27015534, 2016). "The decreased production of TNF may be related to the hyporesponsiveness of PBMCs from patients with severe sepsis or the increased production of an immunosuppressive cytokine such as IL-10." (PMID 27441846, 2016). "The role of anti-inflammatory IL-10 in acute peritonitis or experimental sepsis is controversial." (PMID 26984741, 2016). "IL-10 has been shown to mediate the response of mesenchymal stem cells on macrophages in sepsis." (PMID 27546994, 2016). "Similarly, we found higher levels of the pro-inflammatory cytokine IL-1β in the EBC of patients with altered gas exchange and lower levels of the anti-inflammatory cytokine IL-10 in the EBC of patients with severe sepsis and severe CAP." (PMID 28702287, 2016). "In humans with sepsis, IL-10 concentration has been reported to parallel the excessive production of pro-inflammatory cytokines and sustained overproduction of IL-10 has been associated with poor prognosis, most likely due to the development of a state of immunosuppression." (PMID 26953797, 2016). "Among TLR4+896A/G variant allele carriers with severe sepsis, a significant negative correlation was noted between plasma IL-10 levels and LPS-stimulated HLA-DR expression on CD16- monocyte." (PMID 27861595, 2016). "In order to attenuate the proinflammatory cytokine storm as well as the anti-inflammatory immunosuppressive state, we claim that early reduction of IL-8 and IL-10 might be beneficial in sepsis." (PMID 26612199, 2015). "IL-10 is an important anti-inflammatory cytokine that can temper the immune response during sepsis." (PMID 25844479, 2015).